BRD2 (bromodomain containing 2)
Diseases named in the same sentence as BRD2 in open-access papers (continued):
Sharing a sentence is not in itself a finding about the gene and the disease.
cancer (continued). "BET proteins (BRD2, BRD3, BRD4 and BRDT) serve as the readers of DNA acetylation and regulate the expression of key genes in cancer." (PMID 38893083, 2024). "We used the Genomics of Drug Sensitivity in Cancer database to evaluate the inhibitory effect of BRD4-targeted drug PFI-1 and (BRD2, BRD3, and BRD4)-targeted drug I-BET-151 on ACC cell lines." (PMID 36793283, 2023). "The transcriptional levels of BET (BRD1,BRD2,BRD3, BRD4 and BRDT) were compared between cancer and normal samples in GEPIA database." (PMID 36711038, 2023). "Bromodomain and extracellular terminal (BET) family (including BRD2, BRD3, and BRD4) is considered to be a major driver of cancer cell growth and a new target for cancer therapy." (PMID 36793283, 2023). "We first compared the expression levels of BRD2, BRD3, and BRD4 in ACC patients with different cancer stages and found that BRD3 and BRD4 transcript levels were significantly upregulated in patients with ACC." (PMID 36793283, 2023). "We first compared the expression levels of BRD2, BRD3, and BRD4 in ACC patients with different cancer stages and found that the BRD3 (stage 4) and BRD4 transcript levels were significantly upregulated in patients with ACC (P < 0.05)." (PMID 36793283, 2023). "The BET protein family, including BRD2, BRD3, and BRD4, play an important role in cancer, among which BRD4 protein is involved in regulating cancer and inflammatory processes." (PMID 34943817, 2021). "Although various BET inhibitors are undergoing clinical trials for the treatment of cancer and inflammatory diseases, it has to be noted that BET inhibitors target all BET family proteins, including Brd2, Brd3, and Brd4." (PMID 33830083, 2021). "The abnormal manifestations of BET family members, especially BRD2 and BRD4, occur in various cancer types." (PMID 34540687, 2021). "First, Brd2 is overexpressed in several human tumors (TCGA database), and overexpression of Brd2 (and other BET proteins) promotes cancer in mice." (PMID 32559200, 2020). "HDAC1 and BRD2 were highly expressed in PDA compared to normal pancreas, both in humans and in epithelial and mesenchymal cancer cells in KIC mice." (PMID 33244070, 2020). "Intriguingly, we found two bromodomain containing proteins (BRD2 and BRD3) noted to be relevant in cancer interacting with MALAT1." (PMID 32050583, 2020). "PROTACs have shown the capability of degrading specific Bromodomains like BRD2 and BRD4 that play a key role in cancer progression." (PMID 33086530, 2020). "Therefore, inhibition of BET family proteins, including BRD2, BRD3, BRD4, and BRDT, represents a promising epigenetic approach for various cancer treatments." (PMID 40937321, 2025). "JQ1 may exert its antiproliferative effect by suppressing BRD2 in solid tumors, including NSCLC, where, though, its clinical utilization is severely limited by a different sensitivity among cancer cell subtypes." (PMID 40652527, 2025). "Separately, BRD2/BRD4 affects oncogenes, including MYC, related to cancer." (PMID 40937321, 2025). "The inhibition of BRD2, BRD3, and BRD4 shortens signaling between super-enhancer regions and oncogene target promoters, resulting in cell-specific inhibition of oncogene expression and ultimately cancer cell death." (PMID 36793283, 2023). "While BRD4 is the most studied among BET proteins, there are several reports indicating that BRD2 and BRD3 might also play an important role in dysregulating oncogenes in cancer." (PMID 34440844, 2021). "Conversely, perturbations that may promote aberrant stem cell-like activity and impair differentiation (cancer-promoting genes) included bromodomain-containing proteins (BRD1, BRD2), histone acetyltransferases (EP300), and histone lysine methyltransferases (KMT2C, NSD1, SETD1B)." (PMID 38472198, 2024). "Therefore, BRD2, BRD3, and BRD4 may be biomarkers for some cancers, and the development of their inhibitors may be a potential strategy for cancer treatment." (PMID 36793283, 2023).
cancer (continued). "Therefore, histone acetylation binding by BRD2 and other BET proteins may present an important pharmacological target for the treatment of human cancers, infectious diseases and modulation of immune-inflammation responses 51,86,87." (PMID 35410381, 2022). "Moreover, because JQ1 also inhibits BRD2, BRD3, and other BET family members, in the future it will be important to test the extent to which BET family members contribute to JQ1 anti-tumor activity in HCC and other cancers." (PMID 26575167, 2016). "Finally, it is worth noting that diverse types of cancer cells are “addicted” to high BRD4 levels to maintain a pro-proliferative transcriptional program, which could negatively impact the expression levels of BRD2 and BRD3, which in the case of BRD3 could contribute to increased proliferation." (PMID 30554943, 2019). "Unlike inflammatory function, where both BRD2 and BRD4 were found to play a role in the regulation of cytokine genes, we show that when only BRD4 is perturbed do we see a significant reduction in the ability of NK cells to eliminate cancer target cells." (PMID 33717143, 2021).
tumor (41 papers, 2009 to 2026). "The expression of BRD2 was then validated in 30 human GC tissues and 30 human normal tissues and it was significantly higher than tumor than in normal tissues." (PMID 39744419, 2025). "BRD2 was then validated in 17 HP-positive and 17 HP-negative GC tumor tissues and BRD2 was highly expressed in HP-negative GC tissues." (PMID 39744419, 2025). "We demonstrated that BET proteins, including BRD2, 3, and 4, were aberrantly upregulated in uLMS and exhibited an important tumor-promoting role in uLMS." (PMID 39273015, 2024). "Another recently developed CRBN-based PROTAC dBET1 has also shown very potent activity in degrading BRD2, BRD3, and BRD4 proteins in association with a potent anti-tumor activity in various AML cell lines." (PMID 36909156, 2023). "Various spontaneous tumor models (such as the Eμ-Myc, Eμ-BRD2, or Bcl6 mouse models) have been developed to study how B-cell lymphomas arise and mature in different tumor environments." (PMID 34207773, 2021). "By contrast, overt morbidities were reduced in Brd2 heterozygous animals, with the most marked decreases being in tumor incidence and nephropathology." (PMID 32559200, 2020). "Retroviral insertions were present in the mouse homologs of 10 genes tagged in the zebrafish tumor samples: Brd2, Cirbp, Fgf8, Hexim1, Map2k5, Mmp14, Ncoa2, Slc30a5, Sox4, and Sox5." (PMID 21533036, 2011). "Brd2 and Brd4 have been extensively studied in the context of cell-cycle control and transcription elongation and activation and are known to be overexpressed in multiple tumor types." (PMID 33015071, 2020). "In other hematologic malignancies, JQ1 may exert anti-tumor ability through targeting BRD2, as BRD2 is the critical mediator for STAT5 activity." (PMID 25849938, 2015). "Consequently, dysregulated BRD2 may enhance oncogene transcription and promote tumor progression, contributing to therapy resistance." (PMID 40432836, 2025). "Thus, the apparent tumor-inhibition in the HET mice could be due to Brd2’s function as an important cell cycle regulator." (PMID 32559200, 2020). "Thus, we investigated whether BRD2 contributed to the transcriptional regulation of pro-cachectic factors such as IL6 or PTHrP in the tumor." (PMID 29167426, 2017). "In a colorectal cancer model, PROTAC-mediated degradation of BET proteins (BRD2, BRD3, and BRD4) in tumor cells induces immunogenic cell death and activates DR5-mediated apoptosis." (PMID 41583469, 2025). "BRD4 promotes pro-tumor M2-like polarization by driving MAF transcription, whereas BRD2 contributes predominantly to pro-inflammatory gene expression." (PMID 41583469, 2025). "The BRD2 and BRD4 up-regulation in the GBM models prompted us to better characterize the BET protein involvement in tumor progression, taking advantage of the well-characterized and specific pan-inhibitor JQ1." (PMID 37108181, 2023). "The results indicated that the expression levels of BRD2, BRD3, BRD4 were higher in GBM tumor tissues than those in normal tissues, and BRDT expression in tumor was lower than that in normal tissues." (PMID 36711038, 2023). "A very recent study in AML reported a highly promising PROTAC compound MZ1, which targets and efficiently degrades BRD2, BRD3, and BRD4 proteins in various AML cell lines, and markedly suppress tumor growth in a xenograft mouse model." (PMID 36909156, 2023). "The results showed that treatment with a single dose (5 mg/kg) of BETd-260 for 24 h significantly suppressed the expression of BRD2, BRD3 and BRD4 in tumor tissue of both HCC models." (PMID 31993368, 2019). "Western blotting showed that BETd-260 treatment completely depleted BRD2, BRD3, and BRD4 proteins in the tumor tissue." (PMID 31653826, 2019).
tumor (continued). "We revealed a direct role for BET proteins both in skeletal muscle and in the tumor, by showing direct recruitment of BRD4 and BRD2 at a subset of pro-atrophic genes and pro-cachectic mediators." (PMID 29167426, 2017). "Although p300, BRD2, and G9a interact with the same Runt domain of RUNX3, these data suggest that cells undergo differential lysine modifications of RUNX3 through interactions with these proteins to adequately adapt them to the varying tumor microenvironment." (PMID 33116296, 2021). "The mRNA levels of BRD3 and BRD4 were significantly higher in primary of tumor (TP) versus normal tissue (NT), while there was no significant change of BRD2 mRNA levels in NT vs. TP." (PMID 29434197, 2018). "In the other hand, BRD2 and BRD4 proteins were found to co-occupy with H3K27M-K27ac, then logically, the BET inhibitor was also demonstrated could efficiently inhibit tumor progression." (PMID 29118968, 2017). "GSK2801 displaces BRD2 at the promoters of genes regulated by ETS (E26 transformation-specific) transcription factors and at 45S ribosomal DNA promoters, which induces caspase-3 activity and PARP cleavage, leading to apoptosis of tumor cells in the 3D cultures." (PMID 41278204, 2025). "In contrast, knockdown of BRD4 but not of BRD2 impairs NK cell cytolytic responses, suggesting BRD4 as critical regulator of NK cell mediated tumor cell elimination." (PMID 33717143, 2021). "While it has no significant tumor suppressive effect as a single agent, GSK2801 showed a strong synergistic activity along with the BET inhibitor JQ1 in several TNBC cell lines by targeting BRD2 (Bromodomain-containing protein 2), which is co-regulated along with BAZ2A/B." (PMID 41278204, 2025).
infection (9 papers, 2013 to 2025). The state of being infected such as from the introduction of a foreign agent such as serum, vaccine, antigenic substance or organism. "The remaining 6 compounds increasing infection include histone lysine-methyl binding proteins, prolyl hydroxylase inhibitors, and chromatin-associated bromodomain family member BRD2/BRD4 inhibitors." (PMID 28114951, 2017). "Knocking out BRD2 or inhibiting BRD2 with small molecules strongly inhibited the infection and growth of the virus, and also resulted in marked downregulation of genes involved in the type I IFN response." (PMID 37193304, 2023). "Indeed, the computed top DEG, typifying each cluster on day 3 in the effector phase of infection, hosted several interferon-induced anti-viral genes (Irf1, Irf7, Ifrd1, Socs1, Socs3, Ifit1, Bst2, and Isg15) as well as genes associated with mature resident Trm cells (Cd69, Nfkbid, Brd2, FosB)." (PMID 35260804, 2022). "Western blot and qRT-PCR confirmed that 26695 infection could significantly decrease the expression of BRD2 in AGS and MKN-45 cell lines." (PMID 39744419, 2025). "Inhibition of the bromodomain proteins BRD2/BRD4 by compounds PFI-1 and (+)-JQ1 were found to increase infection." (PMID 28114951, 2017).
metabolic disease (4 papers, 2017 to 2023). A congenital disorder (due to inherited enzyme abnormality) or acquired (due to failure of a metabolically important organ) disorder resulting from an abnormal metabolic process. "For this reason, BRD2 has attracted increasing attention for its critical role in regulation of cellular metabolism and metabolic diseases." (PMID 35694272, 2022).
neurodevelopmental disorder (2 papers, 2013 to 2023). A behavioral and cognitive disorder with onset during the developmental period that involves impaired or aberrant development of intellectual, motor, or social functions. "Here, we use the roles of BRD2 and BRWD3 in neurodevelopmental disorders as examples." (PMID 23425632, 2013).
neurological disorders (2 papers, 2021 to 2022). "Interestingly, several genes encoded in the HLA locus, which has been implicated in SCZ and other psychiatric and neurological disorders, were picked up by our inference downstream of the identified transcription factors (HLA-DOA, HLA-DOB, HLA-DRB1, HLA-DMA, and BRD2)." (PMID 36344995, 2022).
cardiovascular diseases (1 paper, 2022). "In this study, we revealed that BRD2 exerted pro-hypertrophic effects via regulating cardiac energy metabolism, thus expanding our understanding of BETs in cardiovascular diseases." (PMID 35694272, 2022). "Considering the existent structural and functional differences between BRD2 and BRD4, it raises our interests to explore the role of BRD2 in cardiovascular diseases." (PMID 35694272, 2022).
hematological malignancies (1 paper, 2020). "Since bromodomain and extraterminal (BET) proteins (such as BRD2 and BRD4) regulate MYC‐dependent transcription, various potent and selective small‐molecule inhibitors of these proteins have been developed and clinical trials are currently ongoing in hematological malignancies." (PMID 32623836, 2020).
hematological tumors (1 paper, 2025). "BRD2, a member of the bromodomain and extra-terminal (BET) family, plays a crucial role in hematological tumors." (PMID 41048997, 2025).
neurodegenerative disease (1 paper, 2023). A disorder of the central nervous system characterized by gradual and progressive loss of neural tissue and neurologic function. "Brd2 is a Histone Acetyl Transferase (HAT), which plays an important role in the treatment of PD and other neurodegenerative diseases by inducing histone H3K27 acetylation and leading to chromatin opening and enhancing neuronal gene expression." (PMID 36813848, 2023).
BRD2 also shares sentences with these, for which no sentence is quoted: type 2 diabetes mellitus (5 papers); Hyperinsulinemia (3); generalized epilepsy (2); Glucose intolerance (2); infectious disease (2); Intellectual disability (2); Rett syndrome (2); schizophrenia (2); ACTHomas (1); acute biliary pancreatitis (1); adenocarcinoma (1); adrenocortical carcinoma (1); age (1); amyotrophic lateral sclerosis (1); anemia (1); ankylosing spondylitis (1); anxiety disorder (1); asthma (1); autism spectrum disorder (1); chronic kidney disease (1); chronic myeloid leukemia (1); chronic obstructive pulmonary disease (1); colorectal polyps (1); congenital heart disease (1); cutaneous melanoma (1); developmental delay (1); genetic diseases (1); gonadotroph adenomas (1); heart failure (1); hepatoma (1).
A further 27 diseases each share a sentence with BRD2 in 1 paper.